LGALS3 (galectin 3)
Diseases named in the same sentence as LGALS3 in open-access papers (continued):
Sharing a sentence is not in itself a finding about the gene and the disease.
liver fibrosis (continued). "This study, focusing on LSECs and the molecular bases of endothelial dysfunction during liver fibrosis from different mice models, found that SOX4, LGALS3, SERPINE2, CD52, and LPXN are potential key genes associated with endothelial dysfunction in liver fibrosis." (PMID 39194690, 2024). "Given its involvement in multiple pathological settings, galectin-3 has become a therapeutic target, and genetic or pharmacological inhibition of galectin-3 improved renal dysfunction in different pathological conditions and was also protective in experimental models of liver fibrosis." (PMID 37189804, 2023). "MASH improvement was confirmed in mice fed with cholesterol-enriched Western diet for 24 weeks in which ICOSL deficiency greatly reduced liver fibrosis along with the formation of crown-like macrophage aggregates producing the pro-fibrogenic mediators osteopontin (OPN) and galectin-3 (Gal-3)." (PMID 38077334, 2023). "By stimulating proinflammatory cascades by inflammatory gene expressing and profibrogenic cytokine releasing including Il1b, Tnf, Lgals3, S100a6, S100a4, S100a11, and S100a10, Mac1 was characterized as one of the profibrotic contributors during the liver fibrosis progression." (PMID 37724132, 2023). "LGALS3 levels extensively reflect the degree of liver fibrosis." (PMID 34853163, 2022). "Furthermore, TGF-β1 and Galectin-3 (Gal-3; a unique chimera-type β-galactoside-binding protein of the galectin family) are reported to be the key molecules for liver fibrosis through HSC activation." (PMID 32139740, 2020). "In pulmonary and liver fibrosis, serum concentration of galectin-3 was found to be elevated." (PMID 33076422, 2020). "Mac-2 (galectin-3) binding protein (M2BP) is a glycoprotein that is almost undetectable in normal liver but becomes easily detected in patients with hepatocyte injury as liver fibrosis progresses." (PMID 30161179, 2018). "Furthermore, the degree of hepatic fibrosis was enhanced in MCD-fed AnxA1 KO mice, an effect associated with augmented liver production of the profibrotic lectin, galectin-3." (PMID 24668763, 2014). "The complex carbohydrate drugs were chosen based on the hypothesis that inhibition of galectin molecules, and specifically galectin-3, might prove to be a therapy for liver fibrosis." (PMID 24130706, 2013). "In this model of toxin-induced liver fibrosis, treatment with two galectin protein inhibitors with different chemical compositions significantly reduced fibrosis, reversed cirrhosis, reduced galectin-3 expressing portal and septal macrophages, and reduced portal pressure." (PMID 24130706, 2013). "However, we did find that plasma galectin-3 decreased in patients with greater liver fibrosis." (PMID 40943431, 2025). "Additionally, galectin-3 levels may rise due to increased inflammation and liver fibrosis as DM regulation worsens." (PMID 40292099, 2025). "Galectin 3 contributed greatly to the pathogenesis of hepatic fibrosis, including inflammation and fibrosis caused by non-alcoholic fatty liver disease, whereas GR-MD-02 alleviated liver fibrosis by inhibiting galectin 3 and was well tolerated in phase I studies." (PMID 35656117, 2022). "Likewise, transferring bone marrow-derived monocytes in a model of chronic schistosomiasis leads to reduction of liver fibrosis, and among the various factors analyzed is the decrease in Galectin 3 expression which is important for activation of macrophages with a pro-fibrotic profile." (PMID 34279684, 2021). "LGALS3 plays an important role in MAFLD and its progression to more severe liver disease states, such as liver fibrosis and cirrhosis." (PMID 40124784, 2025). "They found that infection with P. gingivalis exacerbated liver fibrosis by activating hepatic stellate cells (HSCs) to produce transforming growth factor-beta 1 (TGF-β1) and galectin-3 (Gal-3) from both HSCs and hepatocytes." (PMID 40564062, 2025).
liver fibrosis (continued). "Our findings indicate that XCF can significantly reduce the mRNA and protein expression levels of LGALS3 and SPP1 in liver tissue induced by a HFD, thereby alleviating the degree of liver fibrosis in MAFLD mice." (PMID 40124784, 2025). "SOX4, LGALS3, and SERPINE2 were strongly correlated with liver fibrosis grade and liver disease progression, with correlation coefficients (R) as high as 0.62 and 0.84 for SOX4 and 0.54 and 0.73 for LGALS3, respectively." (PMID 39194690, 2024). "Subsequently, we conducted qRT-PCR analysis to examine the expression of five key genes (SOX4, LGALS3, SERPINE2, CD52, and LPXN) in the liver tissues of mice with liver fibrosis." (PMID 39194690, 2024). "Because galectin-3 is increased in mice with MASH and hepatic fibrosis, Western blot and immunofluorescence assays were performed." (PMID 37960230, 2023). "Galectin-3 is required for TGFβ-dependent cell activation; deletion of galectin-3 reduces HSC activation, collagen synthesis and liver fibrosis in a model of CCl4-induced liver injury." (PMID 35805998, 2022). "In consideration of the protective effects of galectin-3 in IBD, galectin-3 antagonists, which are currently being tested as therapeutic options to improve renal and liver fibrosis, are not recommended for patients with PSC-IBD." (PMID 40649879, 2025). "Currently, the impact of galectin-3 inhibitors is under investigation in patients with liver fibrosis, but, thus far, the drugs evaluated have not demonstrated efficacy in improving fibrosis." (PMID 40649879, 2025). "This study identified key regulatory genes for endothelial dysfunction in liver fibrosis, namely SOX4, LGALS3, SERPINE2, CD52, and LPXN, which will provide new targets for the development of therapeutic strategies targeting endothelial dysfunction in LSECs and liver fibrosis." (PMID 39194690, 2024). "Moreover, we identified five key regulatory genes for endothelial dysfunction in liver fibrosis LSECs: SOX4, LGALS3, SERPINE2, CD52, and LPXN." (PMID 39194690, 2024). "Furthermore, mice lacking galectin-3 exhibited protection against liver fibrosis triggered by carbon tetrachloride treatment or non-alcoholic steatohepatitis." (PMID 40649879, 2025). "Therefore, SOX4, LGALS3, SERPINE2, CD52, and LPXN may serve as key regulatory genes for endothelial dysfunction in liver fibrosis LSECs." (PMID 39194690, 2024). "The number of hepatic crown-like structure, which was macrophage aggregation and related to liver fibrosis, was drastically increased and fibrosis area was also increased through upregulating immunoexpression of Phosphorylated Smad2 (key signaling molecule of TGF-β1) and Galectin-3." (PMID 32139740, 2020). "LGALS3, the highest upregulated protein in the livers of Lal−/− mice, is a well-known macrophage marker that plays a critical role in multiple liver pathologies and lysosomal repair, and its expression is upregulated in human liver fibrosis, regardless of etiology." (PMID 37595802, 2023). "It has been reported that galectin-3 (Gal-3) promotes HSC activation and liver fibrosis but Gal-3 did not interact with NRP-1, suggesting Gal-3 regulates HSC homeostasis through distinct mechanisms compared to Gal-1." (PMID 28887481, 2017).
Hypertension (91 papers, 2011 to 2026). The presence of chronic increased pressure in the systemic arterial system. "Three SNPs of ST2 and galectin-3 individually were removed because of their associations with confounding traits, including high cholesterol, hypertension, coronary artery disease and so forth." (PMID 35479285, 2022). "Additionally, binary logistic regression showed that patients with LGALS3 rs4644 AA genotype had 6.5-times-higher risk of developing hypertension (p = 0.013; OR = 6.46; CI 1.34–31.13)." (PMID 35807161, 2022). "Moreover, after adjusting for age, gender, education, DM duration, and the prevalence of hypertension, the association between higher levels of Galectin-3 and increased risk of MCI remained significant, with an adjusted OR of 2.028 (95% CI: 1.570–2.620, p < 0.001)." (PMID 39144658, 2024). "During the multiple linear regression analysis, UA and Galectin-3 plasma levels, age, the existence of hypertension, and treatment with insulin were again directly related to the decrease in eGFR during follow-up." (PMID 40806886, 2025). "A positive correlation of circulating galectin 3 serum levels with impaired blood glucose, high blood pressure and higher values of serum lipids and was found in general population." (PMID 39139163, 2024). "The mean concentration of galectin-3 decreased the most in the group of patients with grade 3 hypertension, from 71.67 ± 42.44 to 50.19 ± 31.53." (PMID 36673621, 2023). "Galectin-3 is also a crucial factor in hyperaldosteronism in combination with hypertension-induced cardiac fibrosis and vascular fibrosis." (PMID 25180794, 2014). "A previous study reported that hyperaldosteronism combined with hypertension stimulated macrophage infiltration in the heart, and enhanced the mRNA level of galectin-3." (PMID 25180794, 2014). "Patients with aldosterone-producing adenoma had a significantly higher plasma galectin-3 level than patients with essential hypertension." (PMID 25180794, 2014). "Then, a multiple linear regression analysis was conducted, which showed that elevated plasma levels of UA, Galectin-3, and NT-proBNP, as well as age, the presence of hypertension, and the use of insulin, among others, were independently and directly related to the percentage decrease in eGFR." (PMID 40806886, 2025). "Our study results also demonstrated that underlying hypertensive disorders were associated with galectin-3 levels, but HTN was not an independent correlate after adjustment of some clinical factors." (PMID 37240626, 2023). "The findings might indicate that galectin-3 leads to AS through undetermined mechanisms other than high blood pressure, hyperinsulinemia, and hyperglycemia." (PMID 37240626, 2023). "Besides, in animal models and in vitro studies, it has been shown that hyperaldosteronism worsens hypertension-induced fibrosis through an increase of inflammatory molecules such as galectin-3." (PMID 35208606, 2022). "Clinical studies have determinated correlations between biomarkers of oxidative stress and LVH: Galectin-3 has increased in patients with LVH related to hypertension and serum oxidized low-density lipoproptein shows correlation with LVH related to chronic kidney disease." (PMID 31067252, 2019). "The findings extend reports linking AMOT with EDS in OSA patients, and provide direct evidence that perturbation of BIRC3 and LGALS3 signaling may play an important role in the mediation of hypertension and CKD in OSA patients, respectively." (PMID 28520763, 2017). "Subgroup analyses revealed that AMOT P130 protein expression was increased in OSA patients with excessive daytime sleepiness, BIRC3 protein expression was decreased in OSA patients with hypertension, and LGALS3 protein expression was increased in OSA patients with chronic kidney disease." (PMID 28520763, 2017). "The causative role of galectin-3 in inducing high blood pressure is not known, but HTN may be secondary to vascular remodeling due to the effect of galectin-3." (PMID 37240626, 2023).
Hypertension (continued). "Compared with participants who had normal galectin-3 level, participants with elevated galectin-3 level were older and had higher SBP, WC, Hs-CRP, total cholesterol, and were more likely to have hypertension." (PMID 38755574, 2024). "This research underscores the importance of galectin-3 in maintaining normal trophoblast function and suggests that abnormalities in its expression or activity could contribute to gestational complications, such as preeclampsia and other hypertensive disorders." (PMID 39200778, 2024). "The current study showed that before treatment, the effective group had lower levels of hypertension, CHD, valvular heart disease, galectin-3, RDW, Hepc, and HS and higher levels of ferritin than the non-effective group (P < 0.05)." (PMID 36348283, 2022). "Univariate logistic regression analysis was done using hypertension, CHD, valvular heart disease, galectin-3, RDW, Hepc, HS and ferritin as independent variables, and the effectiveness of treatment of patients with acute attack of CHF as a dependent variable." (PMID 36348283, 2022). "Multivariate logistic regression analysis was done using hypertension, CHD, valvular heart disease, galectin-3, RDW, Hepc, HS and ferritin as independent variables, and the effectiveness of treatment of patients with acute attack of CHF as a dependent variable." (PMID 36348283, 2022). "Mice lacking Gal-3 (Lgals3−/−) showed improved cardiac function and reduced fibrosis after pressure overload and during hypertension." (PMID 30524200, 2018). "Moreover, we verified AMOT, PLEKHH3, ADAR, BIRC3, and LGALS3 protein over-expressions in the treatment-naïve OSA patients, and discovered a correlation between AMOT/BIRC3/LGALS3 protein expression and the presence of EDS/hypertension/CKD, respectively." (PMID 28520763, 2017). "Patients with low ABIs had a greater prevalence of DM(p = 0.011), elevated CRP and galectin-3 levels (both p<0.001), and lower creatinine (p = 0.012), but no significant disparitiesin gender, hypertension prevalence, smoking, blood pressure, HD vintage, or Kt/Vwere observed between groups." (PMID 39076571, 2024).
thyroid cancer (91 papers, 2004 to 2025). "Galectin-3 has emerged as an important biomarker in thyroid cancer, with implications for risk classification and treatment decisions." (PMID 38501105, 2024). "Galectin-3 is a carbohydrate-binding protein commonly overexpressed in thyroid cancer and can serve as a diagnostic biomarker of thyroid cancer." (PMID 35723359, 2022). "Galectin-3 not only represents a diagnostic biomarker in thyroid cancer but also possesses a promising therapeutic potential for metastatic spread." (PMID 34035807, 2021). "In the last two decades, many efforts have been directed toward developing new potential diagnostic tools for improving thyroid cancer diagnosis preoperatively, and galectin-3 is probably one of the most extensively-studied marker so far." (PMID 29393868, 2018). "Altogether, these data strongly support the potential role of galectin-3 as a reliable diagnostic marker for thyroid cancer diagnosis." (PMID 29393868, 2018). "In this study, we used surgical specimens and two different thyroid cancer cell lines to investigate how Galectin-3 was associated with thyroid cancer cell migration." (PMID 29254179, 2017). "Conversely, the average hypomethylation of five CpG sites in the promoter sequence is associated with high LGALS3 expression in thyroid cancer, and allows to distinguish it from normal thyroid tissues." (PMID 28481247, 2017). "Galectin-3 in association with K-Ras GTP contributes to thyroid carcinoma malignancy in anaplastic thyroid cancer cells." (PMID 29254179, 2017). "Galectin-3 expression has been linked to progression, metastasis and survival of patients with many human cancer types such as breast and thyroid cancers." (PMID 22039439, 2011). "For its pattern of expression in thyroid cancer, galectin-3 has recently been proposed as diagnostic marker of malignant transformed thyrocytes." (PMID 15292926, 2004). "Galectin-3 expression is linked to more aggressive characteristics in thyroid cancer." (PMID 38501105, 2024). "Galectin-3 (Gal-3), which has received significant attention for its utility as a diagnostic marker for thyroid cancer, represents the most well-studied molecular candidate for thyroid cancer diagnosis." (PMID 37608676, 2024). "Moreover, an independent study of the largest thyroid cancer diagnostic marker panel reported to date showed that galectin-3 was the most accurate stand-alone marker for well-differentiated thyroid cancer, compared to 56 different candidate molecules." (PMID 29393868, 2018). "At least theoretically, increasing the LET (linear energy transfer) of the radionuclide linked to the galectin-3-specific probe will generate a tool for immuno-radiotherapy and/or radio-ablation of the so-called “occult thyroid carcinomas” of millimetric dimension." (PMID 29393868, 2018). "Immunohistochemistry revealed tumor marker patterns characteristic of malignancy, including parafibromin and E-cadherin loss and positivity for markers such as galectin-3 and cyclin D1 in parathyroid cancers and TTF1 and CK19 in thyroid cancer." (PMID 40142758, 2025). "Aberrant expression of LGALS3 has been described in a variety of cancers, such as glioblastoma, colorectal cancer, hepatocellular carcinoma, thyroid carcinoma, and pancreatic ductal adenocarcinoma (PDAC)." (PMID 41153387, 2025). "Elevated levels of galectin 3 can also be found in other pathologies such as neoplasms (e.g., malignant thyroid neoplasms) and other fibrotic or inflammatory pathologies." (PMID 38541144, 2024). "The specific molecular processes by which galectin-3 promotes thyroid cancer formation and progression are now being investigated, offering insights into prospective treatment targets." (PMID 38501105, 2024).